TRPM2 (transient receptor potential cation channel subfamily M member 2)
Diseases named in the same sentence as TRPM2 in open-access papers (continued):
Sharing a sentence is not in itself a finding about the gene and the disease.
tumor (continued). "Along with inhibition of TRPM2 by siRNA or 2-APB, the decreasing concentration of calcium was observed in CD38 WT and OE tumor cell than that of control." (PMID 34226519, 2021). "The transient receptor potential cation channel, subfamily M, member 2 (TRPM2), a H2O2-dependent channel, can induce influx of calcium into tumor cells and further lead to cell death." (PMID 34484197, 2021). "Four consistent genes were differentially expressed in tumor tissues compared to normal tissues: two Ca2+-activated channels coding genes were induced (KCNN4, TRPM2) while KCNMA1 and TRPM6 were downregulated during the malignant transformation." (PMID 31010205, 2019). "Male NOD/SCID mice were injected in the left flank with either scramble or TRPM2-KD AGS cells; tumor size was measured twice weekly for six weeks." (PMID 30862883, 2019). "To validate our in vitro data on the role of TRPM2 in AGS cell growth and invasion, we investigated the in vivo impact of TRPM2 silencing on the AGS tumor xenograft growth in NOD/SCID mice." (PMID 30862883, 2019). "We show that TRPM2 is an ion channel located in the cytolytic granule, and co-migrates with CD38 to the immunological synapse upon tumor stimulation." (PMID 25879940, 2015). "TRPM2 serves to couple CD38/ADPR activation with sustained Ca2+ signals and contributes to potentiating NK cell cytotoxicity against tumor cells in the mouse model." (PMID 25879940, 2015). "Although the polycystin and mucolipin subfamilies of TRP channels are all down-regulated in tumor tissues, we also found one up-regulated TRP channel gene (TRPM2) in this study." (PMID 24466154, 2014). "Additionally, it explores the involvement of TRPML1, TRPA1, TRPM2, and TRPV1 in modulating reactive oxygen species (ROS) levels within cancer cells, analyzing the ROS dual role in tumor modulation." (PMID 40813985, 2025). "Specifically, TRPM2 and TRPM3 demonstrate anti-tumor effects in gliomas, while TRPM7 and TRPM8 may play a role in the malignant transformation of gliomas." (PMID 39633507, 2024). "In the current analysis, we first found that TRPM2 correlated strongly with TME in a majority of tumors by evaluating the relationship between TRPM2 expression and three TME-related scores, i.e., Stromal, Immune, and Estimate Score, as well as tumor purity." (PMID 37569287, 2023). "TRPM2 is activated by processes in vivo which increase ADP-ribose (ADPR) production, including oxidative stress, which occurs in tumor cells; ADPR then binds to sites in the TRPM2 C-terminus (NUDT9-H domain) and N-terminus to open the channel by effecting conformational changes." (PMID 36446940, 2022). "Several reports have highlighted the importance of the role of hypoxia in TRPM2’s expression and activity, in particular in the context of hypoxia-induced brain damage, but with little evidence in tumour cells." (PMID 35806388, 2022). "Using the UALCAN database, we further validated the finding that the expression level of TRPM2 was negatively correlated with the prognosis of KIRC patients, in consideration of the tumor subtype, cancer stage, nodal metastasis, and tumor grade." (PMID 35071322, 2021). "Their cytotoxicity requires direct physical interaction with tumor cells and is mediated by hydrogen peroxide (H2O2) released by neutrophils and transient receptor potential cation channel (TRPM2), an H2O2-dependent Ca2+ channel expressed on the surface of cancer cells." (PMID 33954115, 2021). "In addition, to understand if the promotion of cADPR on tumor proliferation, and migration was a generalized phenomenon, we also demonstrated that cADPR could promote cell proliferation and migration in variety of human cell lines which existed the expression of TRPM2." (PMID 34226519, 2021). "In these tumor cell lines, TRPM2 is located in the nuclei, whereas in non-cancerous prostate BPH-1 and HMEC and MCF-10A human mammary epithelial cells, it is localized in the plasma membrane and in the cytoplasm." (PMID 31013784, 2019).
tumor (continued). "To assess whether the defect in B16F10 tumor control was due to NK cell dysfunction, we adoptively transferred IL-2 activated NK cells from TRPM2+/+ and TRPM2−/− mice into B16F10 tumor-bearing TRPM2−/− mice." (PMID 25879940, 2015). "Tumor cell-induced granzyme B secretion and cytotoxicity were also completely absent in TRPM2−/− NK cells." (PMID 25879940, 2015). "The lack of either CD38 or TRPM2 results in a significant increase of tumor formation and reduced survival rates." (PMID 25879940, 2015). "Similar to TRPM2−/− NK cells, Cd38−/− NK cells displayed the tumor-induced initial rise in [Ca2+]i, but failed to maintain the elevated levels (36.1% of AUC of Ca2+ trace in Cd38+/+ NK cells)." (PMID 25879940, 2015). "Although the activation of TRPM2 by ROS in tumor cells is not desirable due to its cell survival-promoting effects, it suggests that pharmacological inhibition of TRPM2 in cancer could be a novel and highly promising therapeutic approach." (PMID 39007141, 2024). "Thus, knock-out of TRPM2 enhances ER stress and suppresses EMT, further inhibiting tumor growth." (PMID 36619219, 2023). "TRPM2 level is highly negative correlated to the overall survival and progression-free survival time in PA patients, however, it is significantly increased in PA tissue as the tumor stage increases." (PMID 34099637, 2021). "Considering that there were no corresponding normal tissue data available for some tumor types in The Cancer Genome Atlas (TCGA), we combined the data from Genotype-Tissue Expression (GTEx) and TCGA databases to investigate the expression level of TRPM2 in 33 cancer types." (PMID 37569287, 2023). "Importantly, in rescue experiments using WT TRPM2 but not the silent E960D TRPM2 mutant, mitochondrial function and tumor survival were restored in vitro and in vivo, suggesting a direct link between TRPM2-mediated Ca2+ influx, mitochondrial bioenergetics, and cancer progression." (PMID 37576339, 2023). "Our in vivo data demonstrated the negative impact of TRPM2 depletion on the tumor growth ability of AGS cells, as reflected by the apparent differences in size between scrambled and TRPM2-KD tumors." (PMID 30862883, 2019). "TRPM2 is a non-selective cationic channel that belongs to the transient receptor potential (TRP) ion channel family, known to play a role in various physiological and pathological processes, including tumor progression." (PMID 40330466, 2025). "A second study analyzed TRPM2 expression in the Tumor Immune Estimation Resource (TIMER) and Gene Expression Profiling and Interactive Analysis (GEPIA) databases: TRPM2 mRNA was elevated in ccRCC compared to non-neoplastic kidney, and TRPM2 upregulation predicted poor survival." (PMID 37240443, 2023).
cancer (74 papers, 2015 to 2026). A tumor composed of atypical neoplastic, often pleomorphic cells that invade other tissues. "A key mechanistic insight from this study is the modulation of TRPM2, a redox‐sensitive calcium‐permeable channel implicated in cancer cell survival, mitochondrial function, and chemoresistance." (PMID 41306344, 2025). "In fact, increased TRPM2 expression has been observed in numerous cancers, and its inhibition has been linked to cancer cell death in vitro and in vivo, implying its role in cancer survival and progression." (PMID 37576339, 2023). "We performed Kaplan–Meier (KM) analysis in pan-cancer, and univariate Cox regression analysis to further assess the survival association between TRPM2 expression and patient prognosis in different tumors." (PMID 37569287, 2023). "TRPM2 has several reported splice variants—how do these help determine its role and functions in cancer cells?" (PMID 37445615, 2023). "In the present study, we utilized resources from multiple databases to perform a comprehensive pan-cancer analysis for TRPM2 to investigate its molecular characteristics, diagnostic and prognostic value." (PMID 37569287, 2023). "Results from TIMER2 supported the positive correlation between TRPM2 expression and the infiltration of TAMs, cancer associated fibroblasts (CAFs), and iTreg cells." (PMID 37569287, 2023). "TRPM2 was also closely associated with the infiltration of multiple immune cells in a broad range of malignancies, and in particular positively correlated with TAM infiltration in all three distinct algorithms." (PMID 37569287, 2023). "Additionally, TRPM2 channels upregulated in cancer and their activation is linked to cancer cell proliferation and metastasis." (PMID 40722879, 2025). "TRPM2 has deficient expression and impaired function in various cancer cells, which may help these cells escape oxidative stress-induced cell death." (PMID 39633507, 2024). "However, ADPR produced extracellularly by CD38 through NAD degradation activates TRPM2, which also plays a role in Ca2+ signalling, linked to the survival, proliferation and metabolic status of cancer cells." (PMID 39364393, 2024). "TRPM2 was aberrantly expressed and associated with unfavorable prognosis across various cancers." (PMID 37569287, 2023). "Additionally, while TRPM2 has been studied in certain types of tumors, its role is still elusive in multiple cancers and its association with antitumor immune response remains to be determined." (PMID 37569287, 2023). "Indeed, dysfunction or dysregulation of TRPM2 has been linked with a range of pathological conditions, including neurodegenerative diseases, cardiovascular diseases, and cancer, thus underscoring its pivotal role in maintaining cellular health and function." (PMID 37576339, 2023). "So we speculate that therapy directed simultaneously at TRPM2 and PARPs would cause the cancer cells death as a result of damage accumulation and the inability to DNA repair." (PMID 32423430, 2020). "Studies show that TRPM2 is associated with various types of cancers, too." (PMID 32423430, 2020). "Pharmacological inhibition of TRPM2 significantly suppresses cancer cell proliferation and increases DNA damage." (PMID 41306344, 2025). "The dual role of TRPM2 in cancer progression and organ injury underscores its relevance as a therapeutic target." (PMID 41306344, 2025). "TRPM2 can maintain cancer cell viability by preserving mitochondrial function, producing ATP, reducing cellular ROS levels, and facilitating DNA repair." (PMID 39027429, 2024). "H2O2 secreted by neutrophils depends on Ca2+ channels to induce cancer cell death by modulating the expression of transient receptor potential cation channel subfamily M member 2, thereby inhibiting cancer cell growth." (PMID 39795864, 2024). "TRPM2 is highly expressed in several types of cancer, including breast, pancreatic, leukemia, suggesting that it enhances the survical capacity of cancer cells." (PMID 39027429, 2024).
cancer (continued). "This dual role of TRPM2 in cell viability and drug sensitivity highlights its potential as a therapeutic target in cancer treatment." (PMID 39027429, 2024). "Our findings support TRPM2 as a potential cancer therapeutic target and warrant further study in this direction including the development of cancer therapy‐optimized TRPM2 inhibitors." (PMID 39044361, 2024). "In fact, inhibition of TRPM2-mediated calcium influx produces altered mitochondria functionality, increased ROS production, and impairment of DNA repair processes in cancer cells." (PMID 37445615, 2023). "The TRPM2 is a secreted glycoprotein that shows a key role in cell survival, cancer progression and drug resistance development." (PMID 37081976, 2023). "Most of these studies were conducted by Naziroglu’s research group, showing that the activation of TRPM2 enhanced the anticancer drug-mediated ROS production and cell death in various types of cancers." (PMID 37576339, 2023). "Taken together, these data indicate that TRPM2 promotes cancer progression by enhancing mitochondrial function and ATP production." (PMID 37576339, 2023). "Although many cancer studies involving TRPM2 investigated Ca2+ influx, a unique aim of this study was to investigate the effects of K+ gating." (PMID 37445615, 2023). "In gastric cancer, inhibition of TRPM2 has been shown to increase the efficacy of doxorubicin and paclitaxel, a widely used anticancer drug in cancer therapy." (PMID 37576339, 2023). "An up-to-date review highlights the pro-tumorigenic behaviors of TRPM2 in several cancers and proposes targeting TRPM2 mediated Ca2+ signaling as a feasible anti-cancer therapy strategy." (PMID 37569287, 2023). "Studies in cancer cells show a paradoxical effect, where antagonism of TRPM2 selectively induces anticancer effects." (PMID 37445615, 2023). "As many studies have investigated TRPM cation channels in a variety of cancer processes, including proliferation and metastasis, calcium gating appears to be central in the functioning of TRPM2, a 1503-amino acid channel that also gates Na2+ and K+." (PMID 37445615, 2023). "Being at the intersection of oxidative stress and Ca2+ systems, TRPM2 has rapidly become a fertile area of investigation for understanding cancer biology and improving cancer therapy." (PMID 37576339, 2023). "Regarding cellular localization, TRPM2 displays a unique subcellular localization in several types of cancers." (PMID 37445615, 2023). "To explore the expression pattern of TRPM2 in multiple tumors, we firstly evaluated the expression of TRPM2 mRNA in pan-cancer and normal tissues based on TCGA and GTEx databases." (PMID 37608401, 2023). "The correlation between TRPM2 expression and drug sensitivity was analyzed in 809 human cancer cell lines using the GDSC2 database." (PMID 37569287, 2023). "In view of the potential impacts of TRPM2 on prognosis and immunoregulation, we further analyzed TRPM2 expression in different molecular and immune subtypes across pan-cancer." (PMID 37569287, 2023). "Although TRPM2 has emerged as a potential therapeutic target in various cancers 15-17, its exact role in ccRCC is still unclear." (PMID 36619219, 2023). "TRPM2 maintains the bioenergy of cancer cells by maintaining mitochondrial activity and increased ROS production." (PMID 37337283, 2023). "These paradoxical effects were shown in a variety of cancers, which indicates a novel role for TRPM2 in these types of cancers." (PMID 37445615, 2023). "In cancers or other disease conditions, the expression of TRPM2 ion channels along with others is significantly altered causing impaired intracellular calcium homeostasis." (PMID 37337283, 2023). "We further conducted Receiver operating characteristic (ROC) curve analysis to investigate the possible diagnosis value of TRPM2 across pan-cancer." (PMID 37569287, 2023).
cancer (continued). "Correlation analysis was performed using the Pearson correlation to screen out the top 300 genes that were most positively and negatively correlated with TRPM2 in each cancer." (PMID 37569287, 2023). "This updated and comprehensive review also analyzes the mechanisms by which TRPM2-mediated Ca2+ signaling can regulate the growth and survival of different types of cancer cells." (PMID 37337283, 2023). "Subsequently, we explored the relationship between TRPM2 expression and genomic variation in pan-cancer through integrating copy number alteration (CNA) and gene expression data." (PMID 37569287, 2023). "TRPM2 inhibition decreases ROS production by modulating Nrf2, decreasing NADH and NADPH production, thus causing cancer cell death." (PMID 37337283, 2023). "Since Ca2+ and ROS have been implicated in autophagic signalling pathways, many groups have investigated the role of TRPM2 in the autophagy of different types of cancer." (PMID 37576339, 2023). "This review aims to focus on recent findings in TRPM2 Ca2+ permeable channel in IR injury and cancers, and its activation mechanism by ROS in different cell types and its associated implications." (PMID 37337283, 2023). "Although the role of transient receptor potential (TRP) ion channel TRPM2 has been studied in many cancers, its function in ccRCC is still unexplored." (PMID 36619219, 2023). "So in regard to its role in cancer cells, how important are potential interactions of TRPM2 with other TRPM channels?" (PMID 37445615, 2023). "Collectively, these findings indicates that TRPM2 plays a pivotal role in cancer survival through a dual role in autophagy, which varies depending on the specific type of cancer." (PMID 37576339, 2023). "Our results suggested a positive connection between TRPM2 and immune checkpoints in most types of cancer, particularly in OV, LIHC, THCA, PAAD, and KIRC." (PMID 37569287, 2023). "Overall, these studies suggest that inhibition of TRPM2 is a novel strategy to increase the efficacy of anticancer drugs and improve cancer therapy." (PMID 37576339, 2023). "TRPM2, as in ion channel, mainly participates in calcium metabolism 12 and plays an oncogenic role in several cancers." (PMID 36619219, 2023). "The relationship of TRPM2 expression with immune and molecular subtypes in pan-cancer was investigated through the TISIDB database." (PMID 37569287, 2023). "Considering that promoter methylation also results in abnormal expression of genes, we further investigated the relationship between DNA promoter methylation level and TRPM2 expression among pan-cancer." (PMID 37569287, 2023). "The expression data of TRPM2 from Oncomine also indicated that TRPM2 was more highly expressed in cancer than in normal kidney tissues." (PMID 36619219, 2023). "Lastly, we examine the current understanding of TRPM2-mediated cancer bioenergetics, oxidant defense, autophagy and response to anticancer drugs." (PMID 37576339, 2023). "The results showed that TRPM2 was generally more highly expressed in cancer tissues compared to the corresponding normal tissues." (PMID 37569287, 2023). "We comprehensively investigated the expression pattern, diagnostic value, prognostic impact, genetic and epigenetic alterations of TRPM2 in pan-cancer." (PMID 37569287, 2023). "In the following section, we highlight current knowledge regarding TRPM2-mediated Ca2+ entry in cancer signaling, from its connection to mitochondrial bioenergetics and redox balance to autophagy and chemotherapy response." (PMID 37576339, 2023). "Transient receptor potential channel TRPM2 is highly expressed in many cancers and involved in regulation of key physiological processes including mitochondrial function, bioenergetics, and oxidative stress." (PMID 36446940, 2022). "In the context of tumourigenesis, TRPM2 is upregulated in several cancers where it mediates Ca2+-dependent pathways promoting cell survival." (PMID 35806388, 2022).